PRMT2IP (PRMT2 interacting protein)
Description:
Negatively regulates microglial inflammatory responses. Inhibits NF-kappa-B signaling by interacting with PRMT2, thereby reducing the production of pro-inflammatory cytokines, maintaining a steady-state in microglia and limiting excessive inflammation.
Synonyms: C15orf39; DKFZP434H132; FLJ46337
Tractability: PROTAC: ubiquitination databases record sites on it.
Gene: Protein-coding gene on chromosome 15 (75,195,623 to 75,212,169, forward strand). Ensembl gene ENSG00000167173.
Subcellular location: Cytoplasm; Nucleus
Subcellular location (Human Protein Atlas): Cytosol
Gene Ontology:
Molecular function: protein binding
Biological process: negative regulation of canonical NF-kappaB signal transduction; negative regulation of inflammatory response
Cellular component: cytoplasm; cytosol; nucleus
Genetic constraint (gnomAD): Loss-of-function variants: 25 observed, 53.1 expected, observed/expected ratio (o/e) 0.47, 90% interval 0.34 to 0.66. The upper end of that interval is the gene's LOEUF score, 0.66, which puts it in group 2 of 6, group 1 being the genes least tolerant of losing a copy. Missense variants: 1,225 observed, 1,307.4 expected, observed/expected ratio (o/e) 0.94, 90% interval 0.89 to 0.98. Synonymous variants: 563 observed, 562.96 expected, observed/expected ratio (o/e) 1, 90% interval 0.93 to 1.07.
Homologues: Orthologues: chimpanzee C15H15orf39 (98% identical), macaque C7H15orf39 (95% identical), mouse 1700017B05Rik (76% identical), rat C8h15orf39 (75% identical), dog C15orf39 (73% identical), guinea pig C15orf39 (73% identical), pig C15orf39 (70% identical), rabbit C15orf39 (65% identical).
Diseases named in the same sentence as PRMT2IP in open-access papers:
PRMT2IP is named in the same sentence as 2 diseases in open-access papers, as found by Europe PMC text mining. Sharing a sentence is not in itself a finding about the gene and the disease.
PRMT2IP shares sentences with these, for which no sentence is quoted: breast carcinoma (1 paper); central nervous system diseases (1).